SMAD3 (SMAD family member 3)
Diseases named in the same sentence as SMAD3 in open-access papers (continued):
Sharing a sentence is not in itself a finding about the gene and the disease.
squamous cell carcinoma (8 papers, 2011 to 2023). A carcinoma arising from squamous epithelial cells. "The selective poor response of squamous cell carcinoma (SCC)‐CAF to the anti‐fibrotic drug nintedanib is available through the TGFβ transcription factor SMAD3 repression, which is driven by SMAD3 promoter hypermethylation." (PMID 36599655, 2023). "TGF-β may also maintain the quiescent state of CSCs by phosphorylating SMAD2 and SMAD3 in squamous cell carcinoma." (PMID 35413945, 2022). "Smad3-/- keratinocytes derived from Smad3-/- neonates and transduced with v-rasHa demonstrated reduction of TGFβ induced cell growth arrest and induction of keratin 8, a marker of simple epithelia and malignant conversion of squamous cell carcinomas." (PMID 22204491, 2011). "We have previously observed that Smad3 mediates the TGF-β-induced expression of MMP-13 and CTGF in human gingival fibroblasts and squamous carcinoma cells." (PMID 23468994, 2013). "Finally, we detected a reduction in Smad3, TAK1 and TGFβRII expression in a cohort of 197 clinical squamous cell carcinoma (SCC) CAFs, suggesting that impaired stromal TGFβ signaling may be a clinical feature of SCC." (PMID 28102840, 2017).
diabetic cardiomyopathy (7 papers, 2016 to 2026). Diabetic cardiomyopathy is a disorder of the heart muscle in people with diabetes. "Smad3 null mice crossed with leptin deficient db/db diabetic mice were protected from the development of diabetic cardiomyopathy." (PMID 26925344, 2016). "Our findings suggested that FST plays an important role in improving diabetic cardiomyopathy by its anti-fibrosis effects through the TGF-β–Smad3 pathway." (PMID 34385917, 2021). "Our findings revealed the cardioprotective role of FST in attenuating diabetic cardiomyopathy through its anti-fibrotic effects through the TGF-β–Smad3 pathway and provided a promising therapeutic strategy for diabetic cardiomyopathy." (PMID 34385917, 2021). "In addition, the TGF-β–Smad3 pathway plays an important role in the pathogenesis of diabetic cardiomyopathy." (PMID 34385917, 2021).
leukemia (7 papers, 2018 to 2026). A malignant (clonal) hematologic disorder, involving hematopoietic stem cells and characterized by the presence of primitive or atypical myeloid or lymphoid cells in the bone marrow and the blood. "Several leukaemia-associated oncogenes, EVI1, RUNX1-EVI1 and RUNX1-ETO, interact with Smad3 to repress TGFβ signaling in AML and chronic myeloid leukaemia." (PMID 30367089, 2018). "Homoharringtonine exerts antitumor effects by inhibiting the synthesis of target proteins, such as phospho-eIF4E, SP1/TET1/5hmC, Smad3, and TGF-β pathway components, and NF-κB repressing factor, and promotes apoptosis in leukemia cells." (PMID 35873796, 2022).
liver disease (7 papers, 2017 to 2025). "The expression of C‐terminal phosphorylated Smad3 (pSmad3C) is down‐regulated with the progression of liver disease." (PMID 32406200, 2020). "In summary, we have developed a new animal model that will help future research on the effects of domain‐specific phosphorylation of Smad3 during liver disease progression." (PMID 32406200, 2020). "Domain‐specific phosphorylation of the Smad3 protein is known to be closely related to the development of liver disease." (PMID 32406200, 2020). "MicroRNA-21 and microRNA-145 are reported to be up-regulated and down-regulated respectively in liver disease as reviewed elsewhere, however, how these functionally opposing microRNAs interact with Smad3 in HCC remains veiled." (PMID 29156696, 2017). "We therefore hypothesized that the inhibition of TGFβ1/SMAD3/NOX4 pathway could be a potential mechanism by which GSH enhances ADSC engraftment efficiency in liver diseases." (PMID 40060764, 2025). "Therefore, inhibiting the TGFβ1/SMAD3/NOX4 pathway is an effective strategy to reduce ROS generation in liver diseases, and the correlative work deserves further study." (PMID 40060764, 2025). "Thus, to further investigate the role of Smad3 C‐terminal phosphorylation in the development of liver disease, we generated a mouse model that expresses low levels of pSmad3C." (PMID 32406200, 2020). "Unfortunately, a complete loss of Smad3 causes many side effects, and we therefore could not use this as an model animal to study the molecular mechanisms of liver disease progression." (PMID 32406200, 2020). "More importantly, signaling pathways such as Nrf2, NF-κB, PI3K/Akt/mTOR, NLRP3, Wnt/β-catenin, TGF-β1/Smad3, AMPK/SREBP, PPARα/γ, MAPKs, and Caspases are identified as key targets through which API exerts its beneficial effects in various liver diseases." (PMID 39749193, 2024). "Although the complete upstream signaling pathways of NOXs remain unknown, TGFβ1/SMAD signaling pathway, a well‐known regulator in the progression of liver diseases, has been shown to regulate NOX4/ROS pathway in a SMAD3‐dependent manner." (PMID 40060764, 2025).
rectal cancer (7 papers, 2017 to 2023). A primary or metastatic malignant neoplasm that affects the rectum. "We previously found RUNX2, particularly interactions between these SNPs in RUNX2 and SMAD3, showed strong interaction to increase risk for rectal cancer, as well as prognostic implications." (PMID 28061442, 2017). "We have previously reported that SMAD3 was associated with survival in rectal cancer." (PMID 28061442, 2017). "Moreover, high SMAD3 expression is correlated with favorable prognosis in patients with rectal carcinoma." (PMID 33754062, 2021). "Next, we analyzed pan-cancer data of SMAD3 from The Cancer Genome Atlas (TCGA) and found that SMAD3 expression is significantly downregulated in CRC and rectal carcinoma tissues." (PMID 33754062, 2021). "In addition to SMAD7 (P = 0.0005) and SMAD3 (P = 0.0003), several other genes or genetic regions (CYP2R1, CHAF1A, CREBBP, IL10, SNPs identified in genome-wide association studies (GWAS) to be associated with IGF levels, IGFBP2/IGFBP5, IGFBP3, and C-MYC region) were associated with rectal cancer." (PMID 31434255, 2019).
cardiomyopathy (6 papers, 2016 to 2023). A disease of the heart muscle or myocardium proper. "The hub genes COL4A2/COL4A1/SMAD3 may be potential research targets for cardiomyopathy-associated MI." (PMID 38001896, 2023). "It is also plausible that Smad3 deficiency in other cardiac cell types may have contributed to the observed amelioration of cardiomyopathy in treated animals." (PMID 36269647, 2022). "Among the detectable markers of cardiomyopathy, we evaluated the activation of mTOR, AKT, Smad3, and ERK1/2 to investigate the association of emerin and lamin A/C in the regulation of signaling pathways associated with cardiomyopathy." (PMID 37940872, 2023). "Our data suggest that endothelial cells are a critical target of doxorubicin in the heart and that the TGF-β/Smad3 pathway contributes to the development of doxorubicin cardiomyopathy." (PMID 36269647, 2022). "Our study suggests that the TGF-β/Smad3 pathway contributes to the development of doxorubicin cardiomyopathy and the potential value of novel approaches to ameliorate cardiotoxicity by targeting the Smad3 transcription factor." (PMID 36269647, 2022). "For example, SIRT1 activation has been shown to improve heart function, reduce cardiac fibrosis, and inhibit TGF-β/Smad3 in doxorubicin-induced cardiomyopathy in rats." (PMID 30050588, 2018). "COL4A2/COL4A1/SMAD3 were the hub genes in pericyte function involved in cardiomyopathy and AMI." (PMID 38001896, 2023). "Since Smad3 occupies a central position within this pathway, we examined the role of this transcription factor in the effects of doxorubicin on cardiac endothelial cells and development of cardiomyopathy." (PMID 36269647, 2022).
chronic obstructive pulmonary disease (6 papers, 2018 to 2024). A chronic and progressive lung disorder characterized by the loss of elasticity of the bronchial tree and the air sacs, destruction of the air sacs wall, thickening of the bronchial wall, and mucous accumulation in the bronchial tree. "This miRNA inhibits release of IL-6 and CXCL8 in airway smooth muscle cells in patients with chronic obstructive pulmonary disease by targeting the mothers against decapentaplegic homolog 3 (SMAD3), a key element of the TGF-β1 inflammatory pathway." (PMID 29988529, 2018). "In conclusion, imbalanced Smad3/MRTF signaling is linked to PI hypoxia-induced senescence and pulmonary arterial remodeling, making it a potential therapeutic target for patients with sleep apnea and chronic obstructive pulmonary disease." (PMID 37760802, 2023).
colorectal tumors (6 papers, 2011 to 2022). "Despite the majority of CRCs having deactivating TGF‐β pathway mutations (TGFBR1, TGFBR2, SMAD4, SMAD2, SMAD3), colorectal tumours produce significant amounts of TGF‐β, creating a TGF‐β rich environment, to which only the stromal compartment can respond." (PMID 35595718, 2022). "In contrast, Smad3 homozygous deletion did not affect embryogenesis; however, Smad3-deficient mice developed invasive colorectal tumors that metastasized to the lymph nodes." (PMID 31614493, 2019). "cg24032190, which is located on the gene body of SMAD3, showing that they were hypomethylated in 94.7% (36/38) of CRC paired tissues and 92.0% (289/314) of nonpaired colorectal tumor tissues." (PMID 33036415, 2020).
head and neck squamous cell carcinoma (6 papers, 2016 to 2022). A squamous cell carcinoma that arises from any of the following anatomic sites: lip and oral cavity, nasal cavity, paranasal sinuses, pharynx, larynx, and salivary glands. "Increased expression of MIR211 in head and neck squamous cell carcinoma (HNSCC) inhibited TGFβRII and thus decreased the SMAD3 phosphorylation and increased c-myc expression." (PMID 33628737, 2020). "The same study demonstrated a correlation of SMAD4 knockdown with the downregulation of BRCA1 and RAD51 protein expression in head and neck squamous cell carcinoma (HNSCC) as well as increased expression of TβR1 and phospho-SMAD3." (PMID 33418880, 2021). "DRAK1 is overexpressed and localized in the cytoplasm in head and neck squamous cell carcinomas (HNSCC) and negatively regulates the tumor suppressor function of TGF-β by binding to Smad3 which is required for Transforming Growth Factor Beta (TGF-β) function." (PMID 31330998, 2019). "DRAK1 can interrupt the formation of the Smad3/Smad4 complex by binding to Smad3, a process that inhibits TGF-β tumor suppressor signaling in head and neck squamous cell carcinoma (HNSCC) and increases tumor activity." (PMID 36386181, 2022). "However, in Head and neck squamous cell carcinoma (HNSCC) cell lines, where DRAK1 is overexpressed, DRAK1 in the cytoplasm binds to Smad3 and sequesters it in the cytoplasm, thereby preventing Smad3/Smad4 complex formation and inhibiting TGF-β1 tumor suppression." (PMID 31330998, 2019).
IgA nephropathy (6 papers, 2015 to 2025). "However, numerous tubular cells and α-SMA(+) myofibroblasts exhibited p-Smad3(+) or/and p-JNK(+) staining in biopsy specimens of IgA nephropathy, suggesting that co-activation of Smad3 and JNK1/2 signaling in the tubulointerstitium persisted during the development and progression of CKD." (PMID 31447676, 2019). "A metabolic models like IgA nephropathy, modified EXOs with heparin-chitosan MHCD suppressed TGF-β1/Smad3 signaling and fibrogenesis." (PMID 40524833, 2025). "Immunohistochemical analysis further demonstrated that in the renal tissues of patients with IgA nephropathy (IgAN), several fibrosis-related markers, including TGF-β1, p-Smad3, α-SMA, FN, and collagen IV, were significantly upregulated." (PMID 40442892, 2025). "Co-activations of Smad3 and JNK signaling occur in both tubular epithelial cells and myofibroblasts in areas of tubulointerstitial damage and fibrosis in both murine FA-induced nephropathy and human IgA nephropathy." (PMID 31447676, 2019).
injury (6 papers, 2016 to 2021). Damage inflicted on the body as the direct or indirect result of an external force, with or without disruption of structural continuity. "Recent studies have suggested that the activation of the TGF-β1/Smad3 pathway was associated with CCl4-induced acute liver injury; overexpression of TGF-β1 or Smad3 promoted a CCl4-induced inflammatory response and apoptosis in the hepatocyte of a mouse." (PMID 29351226, 2018). "As elevated inflammatory cytokines are associated with fibrogenesis, we assessed the impact of TNF-α inhibition on ERG expression and SMAD3 activity by co-administration of the TNF-α antagonist etanercept in an acute CCL4-induced liver injury." (PMID 29026072, 2017). "It was reported that TGF-β1 protein level was elevated significantly in CCl4-induced chronic liver injury in mice, and recent study has revealed that Smad3 mRNA expression increased in CCl4-induced acute liver injury in mice." (PMID 27224286, 2016). "However, the TGF-β1 protein expression and the effect of TGF-β1/Smad3 signaling on CCl4-induced acute liver injury are still unclear." (PMID 27224286, 2016).
sarcopenia (6 papers, 2012 to 2026). Progressive decline in muscle mass due to aging which results in decreased functional capacity of muscles. "By using ML algorithms and expression analysis techniques, this study further validated several URGs including CBLB, PSMD6, RNF115, SMAD3, UCHL3 and ZBTB16 as potential markers associated with sarcopenia." (PMID 41560007, 2026).
skin cancer (6 papers, 2011 to 2023). "Loss of SMAD3 and decreased senescence were then shown to promote skin tumor progression." (PMID 38008756, 2023). "Compared with Smad3, Smad2 may play an antagonistic role in the EMT process in vivo: In fact, loss of Smad2 has been frequently shown in human skin cancers, and Smad2 deficiency in keratinocytes promotes EMT accelerating skin tumorigenesis." (PMID 31387321, 2019). "TGFβRII receptor and Phospho-Smad3 expression was correspondingly observed in WAP-Cre; BRCA1KO/CO skin cancer tissues." (PMID 28869585, 2017). "However, we discovered a reduction in the expression of SMAD3 and TGF-β after treating skin cancer with crocin, which is accompanied by improved skin cell morphology and a reduction in the number of tumors." (PMID 37284388, 2023). "Interestingly, skin cancer cell line ANST showed overall diverse behavior, regarding downregulation of Cyclin D1, Myc, and SMAD3 as well as upregulation of MARCKS and RICTOR, compared to all other tested cell lines." (PMID 34722291, 2021). "The Smad3+/- and Smad3-/- mice do not develop spontaneous skin tumors." (PMID 22204491, 2011).
T-cell acute lymphoblastic leukemia (6 papers, 2012 to 2021). Acute lymphoblastic leukemia of T-cell origin. "Among them, the loss of the Smad3 protein has been identified as a key feature of acute T-cell lymphoblastic leukemia." (PMID 34295352, 2021). "It was proven that the loss of Smad3 can work in tandem with a loss of p27KIP1, which is also frequently altered in human T-cell ALL, to promote T-cell leukemogenesis in mice." (PMID 22943793, 2012). "Accordingly, a reduced expression of SMAD3 diminishes the tumor-suppressor function of the TGFβ pathway in a model of acute T-cell lymphoblastic leukemia." (PMID 26700622, 2016). "Additionally, Smad3 protein levels are significantly reduced or even completely absent in childhood T-cell acute lymphocytic leukemia." (PMID 25352951, 2014). "However, the finding that Smad3 protein is absent in T-cell acute lymphoblastic leukemia (T-ALL), which results in an impaired inhibitory effect of TGF-β on T-cell proliferation, supports the notion of a tumor-suppressing role of Smad3 in at least this disease." (PMID 24047375, 2013). "In children T-cell acute lymphoblastic leukemia (ALL), SMAD3 protein is absent or significantly decreased, however SMAD3 mRNA is present in T-cell ALL and normal T-cells at similar level." (PMID 22943793, 2012).
abdominal aortic aneurysm (5 papers, 2015 to 2024). Enlargement and ballooning of the vessel that supplies arterial blood to the abdomen, pelvis and legs. "In our current study, we identify a novel VUS in SMAD3, V244F, in a patient presenting with aortic root aneurysm, right coronary artery ectasia, abdominal aortic aneurysm, right vertebral artery atresia, and cavernoma." (PMID 36926042, 2023). "We describe a novel SMAD3 variant of unknown significance (VUS), V244F, in a patient who presented with aortic root dilation, right coronary artery ectasia, abdominal aortic aneurysm, right vertebral artery atresia, and cavernoma." (PMID 36926042, 2023). "In this study, we investigate the role of SMAD3 in the pathogenesis of calcium chloride (CaCl2)-induced abdominal aortic aneurysms (AAA) in Smad3−/−, Smad3+/− and Smad3+/+ mice." (PMID 25985281, 2015).
adenoma (5 papers, 2015 to 2025). A neoplasm arising from the epithelium. "Further studies of adenoma formation in mice observed a caudal shift of the tumour location from small intestine towards colon after introducing an additional knockout of Smad3 in the ApcMin/+Smad3−/− mouse or a heterozygous mutation of Cdx2 in the Apc+/Δ716Cdx2+/− mouse." (PMID 33292279, 2020). "TGF-β1 addition (390 pM) resulted in the detection of phosphorylated p-Smad2 and p-Smad3 in both the Smad4+/+ and Smad4Δ/Δ adenomas as expected." (PMID 40348815, 2025). "SMAD3, SMAD4, and CEBPB came up as key transcription factors regulating cancer progression at the late adenoma stage." (PMID 36499586, 2022). "For example, SMAD3 (mothers against decapentaplegic homolog 3), a molecule that plays an essential role in TGF-β pathway-mediated EMT, was one of the genes that exhibited increased methylation (log2 fold change = 3.9) in adenomas in Apcmin/+ mice." (PMID 26101583, 2015). "Conversely, both non-tumor BRAFV600E parenchyma and adenomas showed increased pSTAT3 staining compared to controls, thus indicating that BRAFV600E activates STAT3, but not SMAD3, in the lung and potentially suggesting that p21CIP1 may be induced via STAT3 in BRAFV600E lung parenchyma." (PMID 35145078, 2022).
adenomyosis (5 papers, 2017 to 2024). The growth of endometrial tissue inside the muscular wall of the uterine corpus. "Further, TGF-β/SMAD (SMAD Family Member 3) signaling is implicated in adenomyosis’ pathology." (PMID 35207707, 2022). "TGF-β/SMAD3 signaling is a major mechanism involved in endometrial fibrosis and plays a key role in adenomyosis development." (PMID 35207707, 2022). "Specifically, it has been reported that SMAD3 is overexpressed in epithelial cells from eutopic adenomyosis endometrium in secretory phase." (PMID 35207707, 2022). "We further evaluated the total Smad2 and total Smad3 staining of control and each type of adenomyosis." (PMID 29253010, 2017). "The Smad3/2 ratio of Subtype II adenomyosis was significantly higher than that of Subtype I." (PMID 29253010, 2017). "Remarkably, our secretory adenomyosis organoids showed significant TGF-β2 and SMAD3 upregulation compared with controls, confirming successful secretory-phase differentiation and accurate reproduction of specific disease traits." (PMID 35207707, 2022). "Accordingly, our gestational adenomyosis organoids (imitating early pregnancy) showed increased levels of TGF-β2 and SMAD3, recapitulating adenomyosis tissue characteristics." (PMID 35207707, 2022). "Further, patients with adenomyosis present increased TGF-β2 and SMAD3 levels in their eutopic endometrium during the secretory phase compared with disease-free women] SMAD3." (PMID 35207707, 2022). "Adenomyosis organoids showed higher expression of TGF-β2 and SMAD3 and increased gene expression of SPP1, PAEP, LIF, and 17βHSD2 compared with control organoids." (PMID 35207707, 2022). "In our study cases, TGF-β1/ TGF-β1 receptor expressions with a higher Smad3/Smad2 ratio was observed in Subtype II adenomyosis cases, while Subtype I cases showed no significant modification of TGF-β1signaling proteins." (PMID 29253010, 2017).